KCNK15-AS1 (KCNK15 and WISP2 antisense RNA 1)
Synonyms: RP11-445H22.4; LINC01260
Gene: Long non-coding RNA gene on chromosome 20 (44,656,445 to 44,746,362, reverse strand). Ensembl gene ENSG00000244558.
Diseases named in the same sentence as KCNK15-AS1 in open-access papers:
KCNK15-AS1 is named in the same sentence as 2 diseases in open-access papers, as found by Europe PMC text mining. Sharing a sentence is not in itself a finding about the gene and the disease.
KCNK15-AS1 shares sentences with these, for which no sentence is quoted: Hepatic steatosis (1 paper); steatosis (1).